IL10 (interleukin 10)
Diseases named in the same sentence as IL10 in open-access papers (continued):
Sharing a sentence is not in itself a finding about the gene and the disease.
infection (continued). "Finally, we show that one of the miRNAs downregulated during infection, miR-21a-5p, affects host control of B. abortus infection by negatively regulating guanylate-binding protein (GBP) 5 and inducing IL-10 expression." (PMID 29942317, 2018). "The results indicated that IL-6, IL-10, TNF-α, TGF-β, and iNOS expression in the infection group was significantly higher than in the control group, an increase of 1.2-fold, 0.29-fold, 0.32-fold, 0.12-fold, and 3.95-fold, respectively, as well as an increase of CD86 (P = .891) and CD206 (P = .303)." (PMID 30170447, 2018). "The increase in IL-10 and decrease in IL-12 suggest that the immune system is not strong enough to confront the infection." (PMID 29634771, 2018). "Unlike live infection, certain doses of HA were shown to increase the anti-inflammatory cytokines IL-10 and TGF-β (n = 6), although this was not statistically significant." (PMID 30192848, 2018). "Correlating to Mtb loads, when BCG primed mice were boosted with LP-ESAT-6 subunit vaccine after infection with Mtb, there were higher levels of IFN-γ, IL-17A, and IL-22 and lower levels of IL-10 compared to BCG-vaccinated mice, demonstrating the increase in protective immunity." (PMID 30386336, 2018). "In the late stage, the levels of IL-10 were found to be elevated irrespective of the geographical location of the patients and the particular genotype of the strain involved in the infection." (PMID 30186271, 2018). "HIF1α deficiency significantly increases the production of IL-10 protein by macrophages following infection but not IL-10 mRNA expression, indicating that IL-10 secretion is regulated by HIF1α through post-transcriptional regulatory mechanisms." (PMID 29483608, 2018). "Our data additionally demonstrate that IL-21 is not highly expressed in Foxp3+TFR cells during LCMV Cl13 infection, further indicating that IL-10+IL-21+Tfh cells are distinct from the TFR lineage." (PMID 30487586, 2018). "However, during remission stage in mice with lymphocytic choriomeningitis virus infection, IL-10 produced by Tregs promotes the maturation of memory CD8+ T cells, which is beneficial for host defense against secondary infections by intracellular pathogens." (PMID 30116243, 2018). "In addition, inhibition of PLC with D609 reduced production of inflammatory mediators, including TNF-α, IL-10, and NO, in LPC-treated cells during H37Ra infection." (PMID 29755479, 2018). "We further show that preventing PD-1 or IL-10 regulatory pathways has no impact on parasite control, although, admittedly infection control is so effective (and thus parasite load so low) that detecting such an impact if it existed would be difficult." (PMID 30419010, 2018). "Minimum adequate models (MAMs) for effects of infection with Mycoplasma gallisepticum isolates VA1994 and NC2006 on house finch expression of cytokines IL1B, IL6, IL10, CXCLi2, and TNFSF15 in internal eyelid (nictitating membrane) across three different time points." (PMID 29403495, 2018). "The liver levels of IL-10 on the sixth day of infection was lower in the absence of C5 when compared to wild type mice." (PMID 29568732, 2018). "A significant positive correlation (r = 0.73, p = 0.003) between IL-10 and IgG4 level was observed in infected children born to infected mother but no such correlation (r = 0.25, p = 0.31) was found in infection free children born to infected mother." (PMID 30252839, 2018). "Reflecting their high frequencies in the total siLP Treg population, GATA-3+Treg dominated in the small intestinal IL-10+ population irrespective of microbial and nematode-infection status." (PMID 30349532, 2018). "Among the cytokines expressed by BMDMs infected with O. tsutsugamushi, the levels of IL-6 and IL-10 were significantly reduced in cells lacking IFNAR at 36 h after infection when compared to those of wild type macrophages." (PMID 30233599, 2018).
infection (continued). "Addition of isotype control antibody, anti-IL-1β, IL-6, or IL-10 antibodies did not significantly affect the generation of T cells expressing IFN-γ or TNF-α during in vitro infection and T cell priming." (PMID 30233599, 2018). "We also found that dietary IMI slightly increased circulating IL-10 in a manner that was independent of infection status." (PMID 30072754, 2018). "The concentration of the Th2 cytokine IL-10 was significantly lower (1462±265 vs 1761±753 pg/ml, p = 0.031) in cell culture supernatants from the BCG+ group compared to the BCG- group on day 3 post-infection." (PMID 30204787, 2018). "The resistance of these mice to experimental infection was attributed to the absence of IL-10 secreting B1 cells and high levels of IFN-γ." (PMID 30197647, 2018). "Yet, transcription of anti-inflammatory cytokines IL10 and TGFβ was not different in tamoxifen-treated infected MerCreMer+/+ and Mer+MyD88flox+/+ mice along the acute infection period." (PMID 30067739, 2018). "TLR3 deficiency in mice led to increased synthesis of TNF-α, IFN-γ, and IL-10; however, IFN-β, IL-1β, and IL-6 were secreted into the genital tracts of wild-type mice at significantly higher levels than in TLR3-/- mice during early infection." (PMID 29624589, 2018). "Infection of B6 macrophages with wild type bacteria in the presence of titrated amounts of a neutralizing anti-IFNAR monoclonal antibody specifically and dose-dependently inhibited secretion of IL-10." (PMID 29579113, 2018). "Nevertheless, the previously validated let-7e targets Tnfpaip3, Map2k4, Tbk1, and Tnf were upregulated during L. amazonensis infection, whereas the decrease in Chuk/IKBKA and Il10 expression during infection was not reversed by let-7e inhibition." (PMID 30555476, 2018). "Other cytokines (IL-12p70, IL-10, IL-17A) did not or only marginally change following infection or were even reduced (IL-23, IFNβ)." (PMID 30169526, 2018). "In SIV-infected sooty mangabey monkeys (SMM), IFN-γ elevation was more transient, and IL-10 was more prominent during acute control of SIV infection compared SIV infected macaques that did not control infection." (PMID 29677149, 2018). "For instance, TemLate contain discreet IL-10+ and IFN-γ+ populations by two months after infection." (PMID 29630679, 2018). "In the absence of IL-10, macrophages were able to produce IL-1β and NO in response to infection with A54970 strain, in the same levels as induced by BMDMs infected with A28006." (PMID 30518854, 2018). "As in chickens, IL-10 did not appear to play a significant role during infection in turkeys, but TGF-β4 mRNA expression levels were increased." (PMID 30450097, 2018). "IL-10 production by Treg in mLN increased similarly and strongly in SPF and GF mice upon infection." (PMID 30349532, 2018). "We note that TNFα, IL-6 and IL-10 are induced also by HSV, so their presence may in part be consequent to infection." (PMID 30080893, 2018). "To further assess whether early antigenic or inflammatory signals are responsible for the induction of IL-10+IL-21+Tfh cells during persistent infection, we transiently depleted CD4 T cells at the time of infection." (PMID 30487586, 2018). "On the 28th day of infection and 23 days of treatment, the euthanasia occurred, and the heart preserved for histopathological, oxidative stress (SOD, catalase, TBARs, carbonylated proteins) and plasma (CCL2, CCL5, TNF, IL-10) analyses." (PMID 30365644, 2018). "Human IL-1RA, IL-8, IL-10, IP-10, MCP-1, and MIG, which were upregulated in a subset or all of our RVFV-infected humanized mice, are also upregulated in patients who succumb to infection." (PMID 30028878, 2018). "The mRNA levels of ileal Tnfα, Il-1β, Il-22, Il-10, Foxp3 and RegIIIγ were comparable between Tac and Jax mice regardless of infection status." (PMID 29789574, 2018). "By contrast, production of TNF-α, IL-6, and IL-10 did not change in G2A KO BMDMs with or without LPC treatment during H37Ra infection." (PMID 29755479, 2018).
infection (continued). "With a few responders in each infection group, the serum concentrations of the cytokines TNF-α and of IL-10 showed significant differences between the groups ≥100 epg and 4–99 epg for TNF-α and between 4–99 epg and <4 epg for IL-10 (p ≤ 0.05) for each comparison." (PMID 30619332, 2018). "In the absence of C5, a tendency to lower IL-10 levels were observed on the sixth day of infection (p = 0.055) when compared to B6 C5+/+ mice at the same time." (PMID 29568732, 2018). "Similarly, the second eigenvector represented infection resilience/resistance (EV2, 22%; high WG, low CLS and high IL-10), and the third eigenvector tolerance (EV3, 19%; high WG, high CLS and low IL-10), respectively." (PMID 30463512, 2018). "Finally, among the elevated serum cytokine levels for the acute phase of infection, many were monocyte chemoattractants or secreted by monocytes and macrophages (e.g., CXCL10, CCL2, and IL‐10)." (PMID 30150281, 2018). "In addition, the production of IL-10 was similar between AKT-blocked and WT mice during the early stage of infection (5 dpi)." (PMID 28979269, 2017). "The treatment decreased the IL-10 expression, which may have contributed to the elevated expression of IFN-γ in infection with Y and JLP strains." (PMID 29255475, 2017). "In other organs, modulation of immunopathology by IL-10 during infection is not solely reliant on Treg cell activity." (PMID 28316998, 2017). "Lung inflammation in response to infection with Ft LVS or SchuS4 is observed as early as 24–48 h p.i. and consists of both cellular (for example, PMNs and macrophages) and soluble (for example, IL-10, IL-17, MCP-1, KC, and TGF-β) elements." (PMID 28955505, 2017). "Similar to the results of cytokines’ levels, we found that lung CD3+CD4+IFN-γ+, and CD3+CD4+IL-10+ T cells as well as CD11c+SiglecF+IFN-β+ macrophages were significantly increased before and after the infection with S. pneumoniae in HK1505- or PG1505-treated mice when compared to control animals." (PMID 28848552, 2017). "Here, we found that S. mansoni egg antigens are also able to induce IL-10-producing B cells in vivo, without the context of natural infection." (PMID 28753651, 2017). "Despite the absence of IL-10 production in the peripheral blood in our study, it cannot be excluded that this cytokine is produced locally, at the site of infection or is present in peripheral blood at undetectable levels." (PMID 29023574, 2017). "As the IL-10 levels did not decrease significantly after resolution of infection, the increased IL-10 response to PfRBCs appeared long-lasting." (PMID 28821806, 2017). "Association of elevated virulence with high type I IFN paired with high IL-10 levels may provide a more direct link between high type I IFN responses and impaired host control of the infection." (PMID 29230217, 2017). "IL-10 blockade prior to LCMV infection only results in a modest increase in LCMV-specific CD8+ T cells 8 days after infection, which indicates that IL-10 does not greatly alter antiviral CD8+ T cell priming." (PMID 28316998, 2017). "We also examined whether IL-10 and TGF-β1 represent redundant regulatory mechanisms at the site of infection and found that these cytokines differentially regulate TB granuloma macrophage and T cell subset responses." (PMID 29326718, 2017). "The gene expression of Th1 cytokines (IFN-γ and IL-12B) and IL-10 showed no significant change during early infection." (PMID 29216911, 2017). "Although IL-10 mRNA expression was not modulated after PBMC infection in our study or with the strain Ab4, a previous study has described a moderate increase of IL-10 and IL-4 protein expression after PBMC infection with the strains Ab4, RacL11, and NY03." (PMID 28925977, 2017). "Conversely, IL-10 was detected on day 3 and day 4 post infection of NDV AF2240 and IBS002 in the bursa but none on day 1 and uninfected control." (PMID 28569155, 2017).
infection (continued). "Th17 cells can potentially play opposing roles in immunity to infection, with cells producing IL17 and IL10 considered to play a protective regulatory homeostatic role and Th17 cells expressing IFNγ in the absence of IL10 being associated with pathology." (PMID 28931830, 2017). "When patients were stratified by infection status, we observed increases in TNF-α, CRP, TGF-β, IL-4, IL-6, IL-10, IL-17, and IL-23, and a decrease in IFN-γ in both uninfected and infected patients when compared with control subjects at most of the three time points." (PMID 27682880, 2017). "In contrast, the delayed peak in IL-10 levels and insufficient surge of IFN-γ levels in A(H1N1)pdm09 mice at 7 days post-infection could lead to ineffective exclusion of the viruses." (PMID 28831046, 2017). "The finding that cAMP is involved in the regulation of DC activation is relevant in the context of L. amazonensis infection since it provides an explanation for the lack of role of IL-10 in this infection." (PMID 28791011, 2017). "Since DC-specific IL-10 ablation in P. yoelii-infected mice interfered with the induction of IL-10-producing CD4+ Tr1 cells and resulted in elevated production of pro-inflammatory cytokines, we monitored progression of blood infection by microscopic examination of Giemsa-stained blood films." (PMID 28293237, 2017). "However, infection with L. infantum resulted in an increased expression of FoxP3, CD4+, TGF-β, IL-10, TNF-α and IFN-γ in the colon and jejunum and a reduction of CD8+ and IL-4." (PMID 27094260, 2017). "Masp2−/− mice had significantly lower brain levels of interleukin (IL)-1β (median 3.46 vs. 5.33 ng/mg tissue, P = 0.045), IL-10 (1.04 vs. 1.70 ng/mg tissue, P = 0.038), and TNF-α (9.32 vs. 22.58 ng/mg tissue, P = 0.025) compared to WT mice at 30 h after infection." (PMID 28086930, 2017). "Nevertheless, we found a very low proportion of Tregs in the pleural cavity of infected mice (0.3–0.4%) (data not shown) and very low levels of IL-10 (20–50 pg/mL), indicating a relative contribution of Tregs at this time point of the infection." (PMID 28890718, 2017). "FoxP3+ and IL‐10+ frequency within CD4+ T cells was significantly higher in peritoneal exudate cell PECs and spleen cells of E. multilocularis infected (AE‐WT) mice at 4 months post‐infection (p.i.)when compared to non‐infected WT‐controls." (PMID 28621034, 2017). "We observed only a slight, albeit non-significant, reduction in MHC-II expression levels in the course of infection on both DC subtypes, and this was irrespective of their IL-10 expression." (PMID 28293237, 2017). "There was significant induction of bronchial IFN-γ, CXCL11/ITAC, CXCL10/IP10, IL-15, IL-10, TNFα and IL-5 during infection in allergic asthmatics (all P < 0.05), but not in healthy controls." (PMID 28373098, 2017). "No detectable IL-10, IL-12, and IL-17A mRNA production was observed (data not shown) in any infected group, irrespective of the strain or infection dose." (PMID 28642841, 2017). "Additionally, we compared TNF-α, IL-10, and IL-6 levels between mild and severe cases of ANDV-infection." (PMID 28708900, 2017). "Similarly, a decrease in the frequency of IL-10 positive CD4+ T-cells occurred in lung-derived T-cells at 24 and 48h post-infection." (PMID 28880895, 2017). "In addition, the production of TNF-α, IL-6, and IL-10 was similar between TLR2−/− and WT mice during the early stage of infection (5 dpi)." (PMID 28979269, 2017). "Seven days following peroral infection with 109 CFU C. jejuni strain 81–176 on two consecutive days (i.e., days 0 and 1), however, Nod2 was down-regulated in the large intestines of both WT and IL-10−/− mice (p < 0.001 and p < 0.05, respectively)." (PMID 28752081, 2017).
infection (continued). "We analysed IFN-γ, granzyme B, TNF-α and IL-10 levels in PBMC from individuals cured of CL (CCLm), or with a probable asymptomatic L. major (HHRLm) or L. infantum (HHRLi) infection as well as in naïve control subjects (HLR), following stimulation with rLmlRAB or rLmlRABC." (PMID 28416006, 2017). "In particular, macrophages produce IL-10 in a negative and positive feedback loop to dampen the uncontrolled inflammatory cytokine production during infection." (PMID 28216665, 2017). "Indeed, it has been described that B cells can produce IL-10 after recognition of S. Typhimurium LPS through TLR-4, which is relevant to the early stages of the infection." (PMID 28824622, 2017). "Nevertheless, the expression of IL-10 in the infected non-treated control group of mice was produced during early and late stage (day 5 and day 20 pi) of infection." (PMID 28761478, 2017). "Similarly, regulation of pro-inflammatory cytokines is controlled by the release of IL-10, therefore ups and downs inTh1 inflammatory responses, due to IL-4, and TGF-β initially up and later down-regulates during infection." (PMID 28319123, 2017). "In the persistent-infection status, cytokine production was delayed and was composed of a high ratio of proinflammatory versus anti-inflammatory cytokines, such as IL-6, IFN-γ, TNF-α, and IL-10." (PMID 27799331, 2017). "Studies showed that while active VL cases in Indian subcontinent showed a mixed IFN-γ/IL10 response, asymptomatic infections did not lead to antigen induced whole blood IL10 response while showing a positive IFN-γ reaction." (PMID 29312315, 2017). "On the other hand, S. mansoni treated hMDMs expressed higher levels of CCR7 (M1 macrophages;), produced less IL-10 during infection, showed no elevation in CCL22 and were also more fit to control Mtb." (PMID 28192437, 2017). "Although IL-10 producing T cells specific for both lytic and latent HCMV proteins have been identified in vivo, the mechanisms by which HCMV affects T cell IL-10 secretion during lytic infection are not yet understood in detail." (PMID 28628650, 2017). "Differently from the infection with other Leishmania species IL-10 does not seem to play a relevant role in L. amazonensis infection." (PMID 28791011, 2017). "Up-regulation of IL-10 gene expression occurred in BALF cells after PRRSV infection without any difference between strains, and only a delayed increase observed for the Finistere strain (increase from 4 dpi for Lena and 8 dpi for the Finistere infection)." (PMID 28241868, 2017). "The main function of IL-10 during primary infection appears to be inhibition of MHC II expression by APCs and innate cells, whereas during secondary infection its primarily role appears to be controlling T cell responses and, putatively, the early reactivation of memory CD4+ T cells." (PMID 27630165, 2016). "In addition, cytokine levels at the site of infection, as well as IFN-γ, IL-1β and IL-10 production by antigen-stimulated lymph node cells were similar among groups." (PMID 27056545, 2016). "We revealed that an axis involving type-I IFN and IL-27 promotes the generation of peripheral IL-10-producing T cells that suppress antiviral immunity, suggesting that CMV exploits this immune-regulatory pathway induced early in infection to ensure viral persistence within mucosal tissue." (PMID 27926930, 2016). "IL-10–producing Th1 cells play critical and nonredundant regulatory roles in limiting inflammation and controlling the outcome of many different infections." (PMID 27630165, 2016). "Moreover, the level of anti-inflammatory cytokine expression (IL-10 and TGF-β) increased dramatically after PR8 infection but increased moderately after ST169 infection." (PMID 27525278, 2016).